SOD3 (superoxide dismutase 3)
Diseases named in the same sentence as SOD3 in open-access papers (continued):
Sharing a sentence is not in itself a finding about the gene and the disease.
tumor (continued). "Our results demonstrate a critical role for Sod3 downstream of VEGF-C in mediating tumor progression." (PMID 25358638, 2014). "In our present study, we demonstrate a tumor promotional effect of Sod3 downstream of VEGF-C in that restoration of Sod3 in the VEGF-C KD cells not only partially rescues tumor growth but also rescues metastasis." (PMID 25358638, 2014). "Finally, we analyzed the correlation between tumor invasive character and SOD3 expression in the fibroblasts and ECM within the LUAD TME." (PMID 41028519, 2025). "However, therapeutic targeting of SOD3-rich CAF in the tumor microenvironment has significant challenges." (PMID 41028519, 2025). "SOD3 is an antioxidant enzyme that is usually repressed in the tumor milieu." (PMID 41154660, 2025). "Taken together, these results suggest that high SOD3 expression in CAF may enhance the tumor invasion into lymphatic vessels in LUAD and contribute to lymph node metastasis." (PMID 41028519, 2025). "Furthermore, single-cell transcriptomic analysis of LUAD clinical samples confirms a strong correlation between SOD3 expression in fibroblasts and characteristics of tumor exacerbation, such as lymphangiogenesis and metastasis." (PMID 41028519, 2025). "Taken together, these findings indicate that CAF-derived SOD3 promotes EMT in tumor cells." (PMID 41028519, 2025). "This duality suggests that SOD3 might function as either a tumor facilitator or tumor suppressor, depending on the tumor microenvironment and its interactions during development." (PMID 41028519, 2025). "Interestingly, SOD3-overexpressing groups showed significantly higher tumor volume compared to normal CAF transplanted groups shortly after implantation (day 3, 6, and 9 after transplantation)." (PMID 41028519, 2025). "SOD3 protects against oxidative stress and maintains cellular redox balance, and its downregulation has been associated with increased oxidative stress and induction of EMT, processes linked to tumor metastasis." (PMID 41042257, 2025). "Our findings suggest that SOD3 may be a prognostic factor for LUAD patients, and SOD3-expressing CAF could be a potential therapeutic target to disrupt the stroma-tumor alliance relation in tumor development and progression." (PMID 41028519, 2025). "Notably, RNA sequencing of CAFSOD3 reveals that SOD3-mediated VEGF-dependent tumor progression and lymphangiogenesis are up-regulated." (PMID 41028519, 2025). "It has also been reported that ATOX1 transcriptionally regulates SOD3 expression in diverse types of cells, including tumor-associated macrophages, suggesting that ATOX1 may play a role in tumor progression." (PMID 40721800, 2025). "The SOD3 protein level was statistically downregulated in CRC tumor samples." (PMID 39128081, 2024). "Moreover, SOD3 overexpression reduced Ki67 expression (P < .01) and blocked tumor growth (P < .01) and liver metastasis (P < .001) in mouse tumor model." (PMID 39128081, 2024). "The function of SOD3 in the tumor microenvironment is uncertain." (PMID 39589950, 2024). "Tumor weight and size were remarkably decreased in SOD3 overexpressing groups." (PMID 39128081, 2024). "Indeed, the normalizing effects of SOD3 on the tumor vasculature are dependent on the NO-mediated stabilization of hypoxia-inducible factor (HIF)-2α, a transcription factor that upregulates VE-cadherin and reduces vascular leakage." (PMID 35267534, 2022). "SOD3 is a Cu-containing secretory enzymes, and its reduced content will lead to oxidative stress and epithelial-mesenchymal transformation, thereby enhancing tumor progression." (PMID 36524120, 2022). "The aim of our study was to determine whether SOD3 also affects the expression of laminin-α5 in the tumor vasculature." (PMID 35267534, 2022). "Additionally, there is direct evidence that SOD3 overexpression suppresses growth and aggression in tumor cells both in vitro and in vivo." (PMID 36552527, 2022).
tumor (continued). "Here, these tumor samples were analyzed by immunofluorescence to see whether SOD3 also affects laminin α5 expression in the tumor vasculature." (PMID 35267534, 2022). "Taken together, the SOD3 expression in the stromal cells may have the potential to maintain tumor vessel normalization." (PMID 36359248, 2022). "This bi-transgenic mouse (SOD3EC-Tg) expresses SOD3 specifically in the tumor endothelium." (PMID 35267534, 2022). "The present work shows that SOD3 triggers the transcription of the gene encoding laminin α4 (LAMA4) but represses that of the gene coding for laminin α5 (LAMA5) in ECs in vitro and in vivo, thus changing the laminin α4/laminin α5 ratio in tumor blood vessels." (PMID 35267534, 2022). "Intriguingly, this occurred when SOD3 was produced by tumor or endothelial cells." (PMID 35267534, 2022). "Next, to confirm whether SOD3 expression is correlated with vascular maturation, we performed the multicolor visualization of IHC detection on CD34, SOD3, and VE-cadherin on the tumor tissue specimens of the two xenografts." (PMID 36359248, 2022). "In the tumor microenvironment, antioxidant enzymes such as SOD3 are usually repressed." (PMID 36359248, 2022). "The stromal paracrine secretion of SOD3 then continues to support the proliferation of tumor cells, and, correspondingly, reduces the affinity of tumor cells to tumor stroma by decreasing the expression of chemotactic cytokines, such as IL1α and MCP-1, in the stromal compartment." (PMID 36077709, 2022). "In conclusion, this study shows that SOD3 represses the transcription of LAMA5 in tumor ECs." (PMID 35267534, 2022). "Along with anti-tumor activity, SOD3 also exhibit anti-autoimmune potential." (PMID 33717151, 2021). "The anti-tumor effect of SOD3 is mainly regulated through its antioxidative function." (PMID 33717151, 2021). "It would also important to study how SOD3 affects blood vessels in tumor models in which SOD3 may function as pro-tumorigenic." (PMID 33250894, 2020). "This was unexpected, since SOD3 acts as anti-inflammatory molecule in non-tumor models." (PMID 33250894, 2020). "To confirm the role of endothelial HIF-2α in mediating SOD3 effects on tumor vasculature, we analyzed the result of SOD3 overexpression on Doxo effectiveness in mice lacking HIF-2α in ECs (HIF-2αEC-KO), obtained by crossing HIF-2αf/f42 with VE-Cad-CreERT2 mice." (PMID 29422508, 2018). "Elevation of SOD3 to a level that markedly reduces oxidative radicals in the tumor milieu might thus normalize tumor vasculature as efficiently as perivascular SOD3 expression." (PMID 29422508, 2018). "SOD3 is a soluble, secreted enzyme and hence can diffuse in the tumor tissue." (PMID 29422508, 2018). "Reports are contradictory regarding SOD3 influence on tumor progression and angiogenesis." (PMID 29422508, 2018). "In our model, Lov induced SOD3 mainly in stromal cells in a tumor-specific manner." (PMID 29422508, 2018). "Another pending question is whether SOD3-induced vascular remodeling depends on its expression in a specific tumor compartment." (PMID 29422508, 2018). "Therefore, our data suggest that the growth-promoting characteristics of SOD3 are not limited to the initial benign growth phase of tumorigenesis but are sustained to the end phase of tumor development." (PMID 28216675, 2017). "Therefore, to analyze the expression of SOD3 in tumor stroma, we characterized stromal cells from the thyroid." (PMID 28216675, 2017). "Rather, SOD3-related signal transduction studies might indicate mediators of tumor progression, which could then be useful targets for preclinical and clinical studies." (PMID 27293512, 2016). "The correlation of decreased SOD3 expression with increased malignancy has led to the hypothesis that SOD3 could function as a tumor suppressor that must be silenced to allow the progression of carcinogenesis." (PMID 27293512, 2016).
tumor (continued). "Recent studies have suggested that SOD3 has dose-dependent effects on primary tumor growth and metastasis activity that, however, may depend on the ability of different kinds of tumor cells to detoxify ROS differently." (PMID 27293512, 2016). "Thus, SOD3 might be the potential factor for regulating tumor vascularization in OSCC therapeutic strategy." (PMID 36359248, 2022). "High levels of SOD3 in the milieu of EG7-SOD3 tumors grafted in syngeneic mice or EG7 tumors implanted in SOD3EC-Tg mice were also correlated with a reduction in laminin α5 staining intensity in tumor blood vessels, supporting a role for SOD3/LAMA5 interactions in vivo." (PMID 35267534, 2022). "Whether SOD3 also affects the expression of laminin α5 in tumor blood vessels is unknown." (PMID 35267534, 2022). "In addition, SOD3 overexpression in tumor and endothelial cells was associated with an improved response to the adoptive transfer of tumor-specific CD8+ T cells, suggesting that SOD3 provides a permissive signal for tumor infiltration by these cells." (PMID 35267534, 2022). "We first analyzed whether SOD3 affects the tumor response to chemotherapy." (PMID 29422508, 2018). "We tested whether SOD3 upregulation altered perfusion of the tumor parenchyma." (PMID 29422508, 2018). "We analyzed whether specific endothelial SOD3 expression enhanced tumor response to chemotherapy." (PMID 29422508, 2018). "Tumor-specific stem-like cells (tSTM, cluster 0) exhibited strong upregulation of OLFM4, LEFTY1, SOD3, LCN2, SLC12A2, and MMP7, consistent with proliferative, inflammatory, and invasive phenotypes." (PMID 41282138, 2025). "Using LUAD xenograft models co-implanted with SOD3-overexpressing CAFs (CAFSOD3), we observe an aggressive tumor phenotype characterized by increased lymphangiogenesis and lymphatic vessel invasion (LVI) of the tumor." (PMID 41028519, 2025). "For example, while cytosolic and mitochondrial superoxide dismutase (SOD1 and SOD2) were more abundant in tumor tissue (especially the mitochondrial isoform SOD2), SOD3, the excreted isoform, was significantly more abundant in healthy tissue." (PMID 40461450, 2025). "Using a mouse xenograft LUAD model transplanted with human-derived CAF, we showed that overexpression of SOD3 in CAF induces lymphangiogenesis, resulting in tumor metastasis in the lymph nodes." (PMID 41028519, 2025). "Tumor-specific deep crypt secretory cells (tDCS, cluster 10) demonstrated elevated expression of TFF1, FABP1, CKB, PRAP1, IL32, GPRC5A, and SOD3, and were consistent with secretory lineage plasticity and immune or stress-associated signaling." (PMID 41282138, 2025). "In conclusion, this study demonstrated that SOD3 upregulation inhibited CRC cell growth and metastasis and also limited tumor growth and liver metastasisin vivo." (PMID 39128081, 2024). "Concomitantly, CRC cells also exhibited lower SOD3 expression than normal cells, and SOD3 upregulation suppressed CRC metastasis and tumor growth." (PMID 39128081, 2024). "SOD3 upregulation and PHD-2 reduction thus improve vascular function via the same pathway, which in turn enhances chemotherapeutic drug delivery and tumor shrinkage." (PMID 33250894, 2020). "SOD1 has high overall expression in breast tissue, and its expression is further increased in tumor tissues, whereas SOD2 and SOD3 are expressed at approximately levels twofold lower than SOD1 levels." (PMID 29478325, 2019). "We found lower SOD3 and VEC mRNA levels in CRC than in non-tumor samples, with a positive correlation of levels for these genes in CRC samples." (PMID 29422508, 2018). "We estimated separate H-scores for each marker in each tumor area; values correlated positively for SOD3 and HIF-2α in stroma and negatively in the tumor compartment." (PMID 29422508, 2018). "Additionally, IPA analysis predicted activation of tumor-promoting processes such as EMT, vasculogenesis, and ECM remodeling in SOD3-high fibroblasts from advanced-stage LUAD." (PMID 41028519, 2025).
tumor (continued). "In addition, we report that high SOD3 expression in stroma are of LUAD clinical samples positively related to recurrence and intralymphatic tumor invasion." (PMID 41028519, 2025). "Future studies are needed to develop strategies that selectively inhibit tumor-promoting SOD3 activity without disrupting its systemic protective functions." (PMID 41028519, 2025). "SOD3, and GPRC5A were identified as early marker genes expressed in evolving tumor stem cells." (PMID 41282138, 2025). "Through its suppressive effects on SOD3, a key antioxidant gene, ATP7A may influence tumor progression." (PMID 41042257, 2025). "To evaluate whether the antioxidant enzyme is involved in the different tumor vascularization of high- and low-invasive OSCC, we assessed the SOD3 expression in the two xenografts." (PMID 36359248, 2022). "Indeed, superoxide dismutase 3 (SOD3) was shown to normalise the blood vessels in tumours and enhance transendothelial migration of effector T cells into tumours through promoting the stabilisation of HIF-2α." (PMID 33917287, 2021). "To determine whether the improved, SOD3-induced response to chemotherapy is HIF-2α dependent, we injected Ad-C or Ad-mSOD3 virus and Doxo into tumor-bearing tamoxifen-treated HIF-2αEC-KO or Cre− mice." (PMID 29422508, 2018). "Although Lov alone did not affect tumor growth kinetics, it increased the Doxo antitumor effect in WT but not in SOD3−/− mice." (PMID 29422508, 2018). "Lov induced SOD3 in LLC tumors in WT but not in SOD3−/− mice; this induction was also apparent in tumor sections." (PMID 29422508, 2018). "Lov treatment reduced tumor vessel leakage (dextran extravasation) in WT compared to Vhcl-treated but not in SOD3−/− mice." (PMID 29422508, 2018). "In SOD3−/− mice, Lov treatment did not significantly enhance tumor perfusion compared to Vhcl, although there was a clear trend toward a higher percentage of lectin+CD31+ vessels in these mice." (PMID 29422508, 2018). "In the absence of Doxo, Ad-mSOD3- and Ad-C-injected tumor growth was comparable, which suggested that SOD3 overexpression had no inherent protumor or antitumor activity." (PMID 29422508, 2018). "Furthermore, SOD3 has been shown to affect hypoxia inducible factor HIF-1α signaling, which enables vascular growth, thus regulating tumor progression." (PMID 27293512, 2016). "Colorectal cancer tumor tissues exhibited a higher SOD3 mRNA level than adjacent normal tissues." (PMID 39128081, 2024). "Tamoxifen induced strong SOD3 expression in ~50% of tumor vessel ECs in Cre+ but not in Cre− mice." (PMID 29422508, 2018). "Most SOD3-stained tumor EC showed HIF-2α staining, whereas unstained ECs lacked HIF-2α." (PMID 29422508, 2018). "We further identify superoxide dismutase 3 (Sod3), an antioxidant enzyme, as a downstream effector of VEGF-C and show that it is required for the antioxidative function of VEGF-C in vitro, as well as for the ability of VEGF-C to mediate tumor growth and metastasis in vivo." (PMID 25358638, 2014). "However, since Sod3 is not sufficient to fully rescue the in vivo tumor growth and/or metastasis in response to VEGF-C KD, nor is it sufficient to rescue chemoresistance after VEGF-C KD in vitro, other pathways and/or factors downstream of VEGF-C must be required to fully restore these phenotypes." (PMID 25358638, 2014). "On the other hand, SOD3, which is an extracellular superoxide dismutase, has the same spatial distribution as OXPHOS expression (i.e., lower in tumor region, higher in adjacent non-tumor region)." (PMID 32103057, 2020). "SOD3 and VEC mRNA levels were again lower in CRC than in non-tumor samples, with positive correlation between these genes in tumor samples." (PMID 29422508, 2018). "Lov upregulated SOD3 significantly in ECs and leukocytes isolated from LLC tumors implanted in WT hosts but not in ECs and leukocytes from tumor-free organs from these mice." (PMID 29422508, 2018).
tumor (continued). "Isogenic littermates, Cre+ (SOD3 overexpression in EC; SOD3EC-Tg) or Cre− (no ectopic SOD3 expression), were inoculated with LLC cells, and EC-SOD3 overexpression was induced by two tamoxifen injections; higher tamoxifen doses impaired tumor angiogenesis, independently of SOD3 induction." (PMID 29422508, 2018).